PRL (prolactin)
Diseases named in the same sentence as PRL in open-access papers (continued):
Sharing a sentence is not in itself a finding about the gene and the disease.
migraine (continued). "Dopamine agonists may therefore reduce migraine frequency and severity through two distinct mechanisms, one of which involves prolactin lowering and reduced trigeminal sensitization, and the other mediated by dopaminergic modulation of trigeminovascular signaling." (PMID 41052788, 2025). "In addition, prolactin has been reported to activate immune cells, which may in turn contribute to inflammatory mechanisms in the meninges relevant to migraine." (PMID 41052788, 2025). "Thus, increased PRL levels are considered as a worsening factor for migraine." (PMID 38397400, 2024). "Therefore, additional studies are needed to reach a conclusion about whether PRL could be an effective target in male migraine patients." (PMID 36967387, 2023). "Application of the translation inhibitor 4EGI-1 blocked prolactin-induced sensitization to male sensory neurons and mechanical allodynia in estrus-staged female mice by downregulating PRL expression, suggesting PRL-L receptors could be a therapeutic target for migraine." (PMID 37795389, 2023). "However, further research is warranted on the directionality of PRL alterations in migraine and whether an interplay of both decreased and increased PRL levels plays a role in migraine." (PMID 36967387, 2023). "Thus, elevated PRL levels may potentially worsen migraine symptoms or lead to migraine chronification." (PMID 36967387, 2023). "Because of the inconsistency of prolactin levels in migraineurs, we suggest further investigation of hormone levels such as dopamine, which is a factor in migraine mechanisms and affects prolactin levels, as well as corticosterone levels, which could provide information on patients' stress levels." (PMID 37190874, 2023). "The relationship between PRL and migraine has been investigated for years due to its vascular, electrolyte and fluid-absorbing properties, its effects on dopamine, serotonin (5-HT) and estrogen, and the effectiveness of medications that reduce PRL secretion in the treatment of migraine pain." (PMID 36967387, 2023). "Thus, there seems to be an evident link between blood PRL levels and migraine." (PMID 36967387, 2023). "Additionally, pituitary peptides, such as PRL, may contribute to the effect of estrogen on migraine." (PMID 36967387, 2023). "Nevertheless, future research is needed to elucidate the specific mechanism involved in the sex-specific activity of PRL in pain modulation in order to investigate whether targeting PRL signalling could represent a potential therapeutic approach for pain disorders, including migraine." (PMID 36967387, 2023). "Clinical and preclinical studies have postulated a role for PRL and PRLR in headache disorders, particularly migraine." (PMID 36967387, 2023). "Prolactin has been shown to selectively sensitize female nociceptors, increase the release of CGRP, and when applied to the dura, prolactin has been shown to produce migraine-like pain in female, but not male mice." (PMID 40708951, 2025). "Some studies have reported significantly elevated serum PRL levels in migraine patients compared to those without headaches, while others have observed opposite findings." (PMID 40699640, 2025). "In prolactinomas, however, headaches are not uncommon, and studies link them to high PRL levels and migraine." (PMID 39904877, 2025). "Prolactin testing is not routinely included in BC or migraine follow-up protocols, potentially overlooking a key confounder." (PMID 39634775, 2024). "Both prolactin and CGRP promote migraine-like pain behaviors selectively in female animals." (PMID 38658853, 2024). "PRL produced sustained and long-lasting migraine-like behavior in cycling and ovariectomized female, but not male rodents." (PMID 38658853, 2024). "In contrast to the present study, Masoud and Fakharian (2005) who measured serum prolactin levels during acute attacks in 37 subjects with migraine and 37 with nonmigraine headaches reported that prolactin levels decreased during the acute migraine headaches." (PMID 37190874, 2023).
migraine (continued). "In accordance with our findings, they found no a significant difference between the prolactin levels of migraine subjects in their interictal phase and the controls." (PMID 37190874, 2023). "As opposed to our study, they concluded that serum prolactin was not elevated in the acute phase of migraine." (PMID 37190874, 2023). "PRL-S signaling could be necessary to prime neurogenic inflammation in migraine since isolated sensory neurons taken from both male and female PRL-knockout mice successfully reversed prolactin-induced TRPV1 sensitization upon PRL-S reintroduction." (PMID 37795389, 2023). "Seddighi and Dehghani (2002) gauged the relationship between acute migraine attacks and changes in prolactin in 20 subjects with migraine and 20 subjects with nonmigraine headache." (PMID 37190874, 2023). "One study reported decreased PRL levels in 20 male patients with migraine as compared to 20 male controls with non-migraine headaches." (PMID 36967387, 2023). "The authors did not report if the healthy controls had any headache during prolactin measurement and did not compare ictal to interictal prolactin levels in migraine patients." (PMID 38112066, 2023). "Furthermore, other neuropeptides considered as migraine triggers, such as PACAP-38, induce effects on the PRL system." (PMID 36967387, 2023). "Contrastingly, Masoud and Fakharian reported that serum prolactin levels from 37 migraine patients during migraine attacks were significantly lower compared to not age-matched 37 healthy controls." (PMID 38112066, 2023). "Nonetheless, it has been reported that pituitary-derived hormones, such as prolactin (PRL), and the hypothalamic neuropeptide oxytocin (OT) may play a modulatory role in migraine and contribute to its sex-dependent differences." (PMID 36967387, 2023). "It is not yet clear as if high level of prolactin can only influence the headache phase of a migraine attack or can play a role in prodrome symptoms and aura phases, for example, in migraine with aura." (PMID 34737888, 2021). "Based on these results, they reported that PRL levels and PRLR signals are increased in females in a mouse model for medication overuse headache, suggesting a potential role of the hypothalamus and the neuroendocrine system in the chronicity of migraine, especially in females." (PMID 36967387, 2023). "In addition, after dural administration of PRL, migraine behaviour occurs in female mice, but is absent in male mice." (PMID 36967387, 2023). "However, some studies have shown that prolactin level decreased during a migraine attack; for example, a study comparing 20 men with migraine with 20 men without migraine reported that prolactin levels were lower in patients with migraine." (PMID 34737888, 2021). "Besides the direct link between PRL and (migraine) pain, the relationship between inflammation and PRL raises the question whether blocking PRLR can be used in migraine pain—not only as a preventive but also as a treatment that targets pathophysiological mechanisms of migraine." (PMID 36967387, 2023). "In this respect, PRL promotes increases in CGRP release in female but not in male rodents, inducing female-specific migraine-like behavioural responses, which decrease in the presence of CGRP8-37, a CGRP receptor antagonist." (PMID 36967387, 2023).
rheumatoid arthritis (29 papers, 2009 to 2025). A chronic, systemic autoimmune disorder characterized by inflammation in the synovial membranes and articular surfaces. "Local GCF and synovial levels of PRL seem to be linked to the disease process of both periodontitis and rheumatoid arthritis than serum levels." (PMID 36717425, 2023). "Breastfeeding, through prolactin secretion (including synovial prolactin secretion), seems to be a period of higher risk for rheumatoid arthritis or lupus flares." (PMID 32235676, 2020). "Women who breastfeed after the first pregnancy have a higher risk of developing rheumatoid arthritis, suggesting an active influence from PRL." (PMID 29483903, 2018). "Another large study assembled a cohort of 3,405 cases and 4,111 controls, and suggested an association between the PRL rs1341239 T allele and decreased rheumatoid arthritis risk." (PMID 28152004, 2017). "One study, which included 173 rheumatoid arthritis patients and 123 healthy controls, found evidence that the heterozygous genotype of PRL rs1341239 was associated with increased rheumatoid arthritis risk." (PMID 28152004, 2017). "For example, in rheumatoid arthritis and psoriatic arthritis, PRL can be locally produced by macrophages, T cells and synovial fibroblasts while PRLR is expressed in synovial macrophages, lymphocytes, and fibroblasts." (PMID 37490712, 2023). "The relationship between PRL and rheumatoid arthritis emerged from the adjacent location of the human PRL gene and HLA region." (PMID 29483903, 2018). "Recent studies reported higher levels of PRL in serum and synovial fluid of patients with rheumatoid arthritis." (PMID 29483903, 2018). "Moreover, PRL mRNA expression in the synovial tissue of rheumatoid arthritis patients positively correlates with several clinical disease parameters, which confirm the local PRL effect on disease pathogenesis." (PMID 34358244, 2021). "In addition, in psoriatic arthritis and rheumatoid arthritis patients, prolactin production seems to be increased within the macrophages of synovial fluid, while prolactin receptors seem to be upregulated on synovial tissue." (PMID 32235676, 2020). "Several studies have confirmed that Jolkinolide B (JB), a natural extract derived from a Chinese herb, may exert anti-rheumatoid arthritis (RA) effects via the regulation of Th17 cell differentiation, prolactin signaling pathways, and JAK/STAT signaling pathways." (PMID 40529488, 2025). "In rheumatoid arthritis (RA), pro‐inflammatory cytokines and PRL stimulate RA synovial cells to produce MMP." (PMID 35923071, 2023). "The PRL system has been discovered in synovial tissue of rheumatoid arthritis (RA) and psoriatic arthritis (PsA), patients and has been propose as a new potential therapeutic target." (PMID 34093428, 2021). "A large panel of serum gonadal and adrenocortical steroids, LH, and PRL was analyzed in males prior to onset of rheumatoid arthritis (pre-RA) in comparison to matched cohort control (CN) subjects." (PMID 24371442, 2013). "We aimed to investigate prolactin (PRL) levels in gingival crevicular fluid (GCF), synovial fluid, and serum in patients suffering from moderately active rheumatoid arthritis (RA) with and without periodontitis (P)." (PMID 36717425, 2023). "Moreover, prolactin induces the phosphorylation and activation of the signal transducer and activator of transcription-3 (STAT3), resulting in the downregulation of the osteoclast differentiation induced by proinflammatory cytokines, like IL-1β and IL-6, and rheumatoid arthritis (RA)." (PMID 38338751, 2024).
hypophysitis (27 papers, 2012 to 2026). Inflammation of the pituitary gland. "Anti-PIT-1 hypophysitis is a rare but recently recognised autoimmune pituitary disease, which is characterised by growth hormone (GH), prolactin (PRL), and thyroid stimulating hormone (TSH) deficiency." (PMID 40093006, 2025). "Primary tumors like thymoma and bladder lymphoma can cause a paraneoplastic syndrome, and anti-Pit1-hypophysitis will lead to growth hormone, prolactin, and TSH deficiencies with detectable circulating anti-PIT1 antibodies." (PMID 36982990, 2023). "The biological overlap—combining anterior pituitary deficits (GH, prolactin) and, rarely, AVP‐D—supports its inclusion among plausible pathways to aHO." (PMID 41236025, 2026). "Anti-POU1F1 hypophysitis (anti-POU1F1 antibody syndrome) is a newly described pituitary autoimmune disease characterized by acquired and specific growth hormone (GH), prolactin (PRL), and thyroid-stimulating hormone (TSH) deficiencies." (PMID 41465179, 2025). "This study revealed several key findings: anterior pituitary dysfunction (excluding PRL) improved by more than one axis in 52.5% of cases, whereas 7.5% experienced additional postoperative anterior pituitary deficits." (PMID 40585888, 2025). "Blood routine showed absolute eosinophil count, 0.31×109/L; blood osmolarity, 280 mOsm/L; blood PRL, 257.80 mIU/L; and urine SG, 1.015; dynamic contrast-enhanced MRI scan of the pituitary gland revealed decreased absorption of hypophysitis lesions." (PMID 40547018, 2025). "Serum prolactin measurements are important in the differential diagnosis of pituitary masses and subfertility." (PMID 39422626, 2024). "When lymphoma in the sellar region involves the hypothalamus or the stalk of the hypophysis, it can disconnect the dopamine secretion pathway, which weakens the inhibitory effect of dopamine on the prolactin‐secreting cells of the hypophysis." (PMID 34286902, 2021). "The primary source of systemic PRL is hypophysis; however, several cells and tissues produce extra-pituitary PRL, which acts mainly in an autocrine and paracrine manner." (PMID 34745013, 2021). "For example, the treatment of Wistar rats with bisphenol A (insecticide) in high doses increased the weight of the hypophysis and elevated the prolactin levels compared to castrated rats." (PMID 23509706, 2013). "After the resolution of COVID-19, this moderate elevation of prolactin could be related to the thickening of the pituitary stalk resulting from hypophysitis." (PMID 38392036, 2024). "Excess PRL may result from functional dysregulation of PRL secretion, damage to the hypothalamus, or the presence of a hormonally active pituitary prolactinoma." (PMID 37047464, 2023). "An increase in anti-prolactin and anti-TSH antibodies was detected in patients with hypophysitis after ipilimumab administration." (PMID 40981113, 2025). "Before the clinical administration of drugs, hypophysitis should be evaluated by evaluation of the levels of prolactin, T4, TSH, LH, FSH, ACTH, and cortisol and pituitary inflammation." (PMID 35002724, 2021). "Hypophysitis is a typical endocrine side effect of anti-CTLA-4 agents, since as hypothesized in some studies, CTLA-4 is expressed in prolactin (PRL) and TSH-secreting pituitary cells." (PMID 36612243, 2022). "The elevation of prolactin during COVID-19 could be explained by various mechanisms, including stress, reduced TSH (thyroid-stimulating hormone), inflammatory state, apoplexies, hypophysitis, and other factors that potentiate prolactin release." (PMID 38392036, 2024).
COVID-19 (25 papers, 2020 to 2025). A disease caused by infection with severe acute respiratory syndrome coronavirus 2. "A new RNA endotype classified using high PRL/TLR3 was associated with mortality in COVID-19 patients." (PMID 37966347, 2023). "Since serum T and PRL levels were significantly increased in both basal and all COVID-19 women, their associations with COVID-19 disease were further evaluated." (PMID 33816526, 2021). "Firstly, the relatively small sample size may have limited our ability to detect statistically significant associations between prolactin levels and clinical outcomes in COVID-19 patients, particularly across different patient subgroups." (PMID 39595974, 2024). "We envisage that prolactin may be one of the significant player in trigger of cytokine storm implicated in COVID-19." (PMID 33841751, 2021). "Although various studies have reported elevated PRL expression and exacerbation of viral infections such as those caused by human immune deficiency virus and hepatitis C virus, the mechanisms underlying the high PRL expression in COVID-19 are poorly understood." (PMID 37966347, 2023). "Increased levels of INF-γ, luteinizing hormone, and prolactin have been identified as the underlying cause for recurrent pregnancy losses; thus, these factors not only amplify the severity of the cytokine storm in COVID-19 but also consequentially result in adverse pregnancy outcomes." (PMID 35319475, 2022). "Despite the lack of definitive results, this study is the first to systematically investigate the role of prolactin in the context of COVID-19, as suggested by the previous literature." (PMID 39595974, 2024). "High levels of serum prolactin were observed in patients with active COVID-19 but became similar to a control group after one month and remained stable over time." (PMID 38673504, 2024). "A significant difference was observed inside the group between prolactin concentration levels during the second and third visits compared to the first in the COVID-19 group (p ≤ 0.05)." (PMID 38673504, 2024). "PRL (RR = 2.42; 95% CI 0.52, 4.31; P = 0.01), the PRL in the COVID-19 group was 2.42 ng/ml higher than that in the control group, and the difference was statistically significant." (PMID 38407718, 2024). "At third visit, which was 180 days after entering the study, the levels of prolactin were comparable in all groups (severe COVID-19: 275.74 ± 36.33; mild or moderate COVID-19: 260.85 ± 68.30; control: 275.0 ± 50.29 ng/mL)." (PMID 38673504, 2024). "In contrast, in patients with severe COVID-19, prolactin levels during third visit showed an inverse correlation (p = 0.022) with excitement, hydration (p = 0.004), and FSFI total score (p = 0.030)." (PMID 38673504, 2024). "The mild or moderate COVID-19 group had the highest level of prolactin concentration among all groups during the first visit (466.82 ± 101.79 ng/mL), while the severely ill patients had a mean prolactin concentration of 335.24 ± 43.48 ng/mL." (PMID 38673504, 2024). "The lowest prolactin concentration at this visit was in a group of severe COVID-19 patients (237.40 ± 28.06 ng/mL)." (PMID 38673504, 2024). "Some studies, including our meta-analysis, have also shown that prolactin is significantly higher in patients with COVID-19 than in healthy men." (PMID 38345682, 2024). "During the first visit, patients in the active phase of COVID-19 had noticeably elevated levels of prolactin in comparison to healthy patients (first visit: 422.60 ± 53.18 ng/mL vs. 283.48 ± 32.75 ng/mL)." (PMID 38673504, 2024). "A study of men with COVID-19 reported high PRL and luteinizing hormone levels and low testosterone and follicle-stimulating hormone levels, which indicated primary testicular damage during active disease." (PMID 36833950, 2023). "In this study, whole-blood RNAs (prolactin and toll-like receptor 3) involved in the prognosis of patients with COVID-19 were identified." (PMID 37966347, 2023).